MDM2 (MDM2 proto-oncogene)
Diseases named in the same sentence as MDM2 in open-access papers (continued):
Sharing a sentence is not in itself a finding about the gene and the disease.
sarcoma (204 papers, 1994 to 2026). A usually aggressive malignant neoplasm of the soft tissue or bone. "For example, recent molecular studies emphasize the role of MDM2 amplification in intimal sarcomas as a supportive diagnostic marker with potential prognostic relevance." (PMID 41463197, 2025). "MDM2 is rarely lost or mutated in human cancer cells; however, MDM2 overexpression is frequently observed in various human tumors and cancers including ~30% of human sarcomas, and MDM2 promotes cell transformation." (PMID 39199272, 2024). "We anticipate therefore that a large number of intimal sarcomas will have been misclassified as leiomyosarcomas prior to the finding that MDM2 amplification is a hallmark of these tumors." (PMID 37395142, 2023). "Through cell proliferation arrest and apoptosis induction, navtemadlin prevented the in vivo growth of numerous tumor xenografts and caused complete and durable regression of MDM2-amplified SJSA-1 sarcoma tumors." (PMID 37509518, 2023). "Amplification of MDM2 has been detected in multiple tumours including sarcomas, lung cancer and colorectal cancer, moreover, MDM2 over-expression is also linked to poor prognosis and increased chemotherapeutic resistance." (PMID 34209840, 2021). "The results of this analysis indicated that these sarcomas had very few gene mutations and a high frequency of amplifications of not only MDM2 and CDK4 but also other genes." (PMID 28099935, 2017). "The variant allele of the MDM2_309T/G polymorphism was reported to be associated with sarcomas, including osteosarcoma, by several studies including meta-analyses." (PMID 27566557, 2016). "Furthermore, increased MDM2 expression was associated with an advanced pathological tumor stage, high tumor grade, ureter localization and presence of glandular and sarcoma differentiation." (PMID 39272712, 2024). "Taken together, our data suggest that MDM2-ALT2 may play an oncogenic role in RPLPS, highlighting the importance of expanding the studies of MDM2 alternative splicing variants expression and functions in this highly lethal sarcoma." (PMID 39769278, 2024). "Therefore, high levels of MDM2 expression are often associated with poor prognosis in various types of cancer, including breast, lung, bladder, and sarcoma." (PMID 37297833, 2023). "The amplification of the MDM2 gene in sarcomas is often associated with CDK4 amplifications." (PMID 30206211, 2018). "Furthermore, both mice and humans with elevated levels of Mdm2 due to a high frequency single nucleotide polymorphism in the Mdm2 promoter (Mdm2SNP309) are more susceptible to sarcoma formation." (PMID 23036318, 2012).
sarcoma (continued). "Mdm2 has also been shown to induce expression of the multidrug resistance 1 (mdr1) gene and its main product P-glycoprotein (P-gp), which has been implicated in chemoresistance in human sarcomas." (PMID 15026814, 2004). "To leverage this dependency for targeted eradication of pediatric sarcomas with MDM2 overexpression, we develop MDM2-recruiting proteolysis-targeting chimeras that selectively degrade the CDK9/Cyclin T complex (P-TEFb)." (PMID 42318649, 2026). "Examples of antibodies serving as surrogate markers of sarcoma-specific genetic aberrations, e.g., fusions, amplifications, and point mutations, include SS18-SSX or SSX, TFE3, SMARCB1, BCOR, MDM2, DDIT3, and PAX3." (PMID 40526340, 2025). "Therapeutic interventions aimed at MDM2-amplified sarcoma are presently being evaluated in clinical trials." (PMID 40078190, 2025). "An initial panel of markers should be done to identify the lineage of tumor: carcinoma (cytokeratin AE1/3, OSCAR, CAM5.2), lymphoma (CD20, CD3), melanoma (S-100 protein, SOX10), and sarcoma (desmin, smooth muscle actin, MDM2, ERG)." (PMID 39634259, 2024). "CDK4 gene amplification in sarcomas has been observed in both bone and soft tissue tumors, while MDM2 gene amplification predominates in soft tissue tumors, often without coamplification of other genes in the 12q13-q15 region." (PMID 38275873, 2024). "MDM2 gene locus amplification is a useful molecular finding in the diagnosis of some sarcomas, including LGIOS, parosteal osteosarcoma, and liposarcoma." (PMID 39105970, 2024). "The presence of MDM2 gene locus amplification is a useful molecular adjunct in the evaluation of some sarcomas, including low-grade intramedullary osteosarcoma (LGIOS)." (PMID 39105970, 2024). "The MDM2 (immunohistochemistry-based) tumour marker is considered to be useful for high-grade intimal sarcomas nowadays." (PMID 38732333, 2024). "The survival rate in angiosarcomas was similar when compared to intimal sarcomas; MDM2 positivity was better than MDM2-negative status (p = 0.003) in terms of outcome." (PMID 38732333, 2024). "BI 907828 is an orally administered drug with a long half-life and is being evaluated in various types of sarcomas characterized by MDM2 overexpression." (PMID 38275873, 2024). "Molecular studies revealed a high frequency of MDM2 overexpression and amplifications in intimal sarcomas." (PMID 38656400, 2024). "MDM2 amplification is known to occur in various types of tumors, including sarcomas, carcinomas, and melanomas." (PMID 38275873, 2024). "As also detected in our patient, MDM2 amplification is observed in > 70% of intimal sarcomas, and targeted therapy against MDM2 has shown some promise in small clinical studies." (PMID 38656400, 2024). "For instance, the EWSR1 gene or the MDM2 gene can be rearranged or amplified in various types of sarcomas, carcinomas, or even mesotheliomas." (PMID 38275873, 2024). "Our present study indicated that intimal sarcomas with an MDM2 amplification had a better prognosis than non‐amplified undifferentiated sarcomas." (PMID 37395142, 2023).
sarcoma (continued). "Intimal sarcomas and undifferentiated cardiac sarcomas carry mutually exclusive MDM2, MDM4, and CDK6 amplifications and share a typical DNA methylation signature." (PMID 36983010, 2023). "Overall, p14ARF epigenetic silencing is a valuable target which can affect MDM2 function in sarcoma." (PMID 37297833, 2023). "Consistent with the mRNA evaluation, protein levels of Cdkn1a and Mdm2 were also detectably upregulated in the two W/+ sarcoma cell lines treated with ATO, in a dose-dependent manner." (PMID 38030599, 2023). "The reason for emphasizing the MDM2 test is that if MDM2 overexpression is detected in high‐grade sarcoma, it should be classified as intimal sarcoma, which has a better prognosis compared to UPS, thus, accurate diagnosis by MDM2 test is important." (PMID 37395142, 2023). "MDM2 positive intimal sarcoma showed the better overall survival (p = 0.003) than undifferentiated pleomorphic sarcoma." (PMID 37395142, 2023). "The p14ARF epigenetic silencing event represents a valuable target that can affect MDM2 function in sarcoma." (PMID 37297833, 2023). "Histopathology of the cardiac mass was consistent with a Grade 3 LA intimal (spindle cell) sarcoma with positive staining for Murine Double Minute Clone 2 (MDM2), an oncogene amplified in intimal sarcomas." (PMID 37715284, 2023). "Many common bone and soft-tissue cancers, including sarcomas, have been shown to be amplified by the MDM2 gene." (PMID 37297833, 2023). "The correlation between MDM2 gene amplification in sarcoma and the clinical prognosis of the affected patient is controversial." (PMID 37395142, 2023). "MDM2 amplification is found in many subtypes of sarcomas including osteosarcoma, well differentiated/ dedifferentiated liposarcoma (DDLPS), and rhabdomyosarcoma." (PMID 37395142, 2023). "We extracted the expression profiles of four sarcoma-related tumor biomarkers, MDM2, CDK4, CD34, and TLE1, from the cohorts TCGA-SARC and GSE21050 and analyzed their expression profile in each IMS." (PMID 36153483, 2022). "Gene amplification of MDM2 has been described as the pathway of tumorigenesis or tumor progression in various sarcomas, including OS." (PMID 35070121, 2022). "MDM2 inhibitors have demonstrated robust anti-cancer activity in clinical trials for glioblastoma, sarcoma and various hematological malignancies such as B-cell chronic lymphocytic leukemia." (PMID 35326742, 2022). "At the second recurrence, the pathological diagnosis after biopsy was of sarcoma with MDM2(+) and CDK4(+) immunohistochemical staining results." (PMID 35096429, 2022). "Fusions were mostly occurred in MDM2, which corresponded to the results in a French sarcoma cohort with the other subtypes." (PMID 35586877, 2022). "Five genes are expressed only in this type of sarcoma: PIK3CA, MDM2, HMGA2, EGFR, CDK, CDK4, while CDKN2A is implicated in angiosarcomas and undifferentiated pleomorphic sarcomas only." (PMID 34359782, 2021).
sarcoma (continued). "Some gliomas, carcinomas and hematological malignancies have been described to amplify MDM2, but this feature is most frequently seen in sarcomas, the topic of the review." (PMID 33799733, 2021). "Dedifferentiated liposarcoma (DDLPS) is a highly malignant sarcoma characterized by the co-amplification of MDM2 and CDK4." (PMID 34834427, 2021). "In fact, DDL can mimic any type of sarcoma and MDM2 immunohistochemistry/FISH should be part of the panel of tests in any sarcoma occurring at any site, certainly if it is undifferentiated and pleomorphic." (PMID 33799733, 2021). "In this respect, search for MDM2 amplification/expression can be very useful to distinguish these low-grade sarcomas from their—often benign—mimics." (PMID 33799733, 2021). "In the case of HPVs and Mdm-2, they are mainly involved in genital cancers and sarcomas, respectively." (PMID 33972599, 2021). "The amplification rate of MDM2 in malignant lung, skin, and bladder tumors is lower, whereas that in sarcoma is higher, consistent with the primary resistance of sarcoma to ICIs." (PMID 34290608, 2021). "Human sarcomas with MDM2 gene amplification were the first cancer types to be trialled with MDM2 targeted drugs." (PMID 32874188, 2020). "Five distinct sarcoma translocations and MDM2 amplification were detected in this ctDNA series, with as little as 3.2 ng of cfDNA input." (PMID 33287361, 2020). "We evaluated intra-tumoral kinetics by FLT-PET imaging, to c-MET inhibitors and MDM2 inhibitors in patients with multiple types of sarcoma." (PMID 32106426, 2020). "The MDM2 gene has been found to be amplified in several human tumors, including in situ and invasive breast adenocarcinomas, esophageal cancer, sarcomas (either common bone and soft tissue forms), and endometrial stromal tumors." (PMID 32806555, 2020). "In selected cases, to differentiate from lipomas and other sarcomas, analyses of MDM2 amplification were performed." (PMID 32158531, 2020). "Subsequently, human MDM2 was cloned and also found to be amplified in sarcomas, suggesting its potential role as an oncogene." (PMID 31905981, 2019). "Using mouse xenograft models, we found that the co-overexpression of MDM2 and CDK4 in 5H cells with five additional oncogenic mutations can cause proliferative sarcoma with a DDLPS-like morphology in vivo." (PMID 31160689, 2019). "MDM2 amplification is seen in a panel of cancers, including sarcomas, gliomas, lymphomas, leukemia, and others." (PMID 31905981, 2019). "Mdm2 is a proto-oncogene that plays an essential role in human sarcomas, which is overexpressed in a wide variety of cancers." (PMID 31523185, 2019). "Our data support the use of NGS on intimal sarcomas to identify MDM2 amplification and consideration for such trials." (PMID 31480474, 2019).
sarcoma (continued). "The genes encoding MDM2 and CDK4 are frequently co-amplified in sarcomas, and inhibitors to both targets are approved or clinically tested for therapy." (PMID 30206211, 2018). "In this regard, adipocytic tumors or small superficial tumors require particular attention when diagnosing sarcoma, keeping in mind that the gold standard for adipocytic tumors is MDM2 amplification." (PMID 29621244, 2018). "MDM2 is known to be amplified or overexpressed in 40% to 60% of human sarcomas as well as in several other solid and hematological malignancies." (PMID 30237864, 2018). "Cell lines from several sarcoma subtypes with defined molecular backgrounds, such as GIST with KIT mutations and dedifferentiated LPS with MDM2 and CDK4 amplification, were treated with selinexor to investigate potential mechanisms of action." (PMID 26918731, 2016). "Human sarcomas often exhibit mdm2 gene amplification 6, 7 and such patient groups provide a test‐bed for MDM2 targeted therapeutics." (PMID 27273042, 2016). "Our case, which provides clear evidence of a pleomorphic undifferentiated sarcoma arising from a lower grade tumor with MDM2 amplification, further supports this finding." (PMID 26987706, 2016). "Representative sarcomas with adipocytic differentiation that show MDM2 gene amplifications are defined as DDLS." (PMID 26502919, 2015). "Seven of the 32 (21.9 %) undifferentiated pleomorphic sarcomas with MDM2 amplification were excluded because their biological character is similar to that of DDLS." (PMID 26502919, 2015). "Although it was originally thought that CDK4 is co-amplified with other Chr 12q13-15 genes, such as MDM2, it appears that different genes within this region are amplified dependent on the sarcoma subtype." (PMID 26528855, 2015). "Gene amplification of MDM2 occurs at high frequency in sarcomas and at low frequency in cancers of the brain, bladder, stomach, lung, skin, and breast." (PMID 25730903, 2015). "Intimal (spindle cell) sarcomas usually show positive immunoreactivity for vimentin, osteopontin, and MDM2." (PMID 23424592, 2013). "Of this last group, four were undifferentiated sarcomas and immunostaining for MDM2 and/or CDK4 was positive in three." (PMID 24216705, 2013). "Certain studies have demonstrated that MDM2 and CDK4 were strongly implicated in the pathogenesis of carcinoma and sarcoma." (PMID 23426899, 2013). "The MDM2 proto-oncogene plays a key role in central cellular processes like growth control and apoptosis, and the gene locus is frequently amplified in sarcomas." (PMID 22558411, 2012).